CDK19 (cyclin dependent kinase 19)
Description:
Component of the Mediator complex, a transcriptional coactivator required for regulated expression of nearly all RNA polymerase II-dependent genes. Acts as a molecular bridge between gene-specific regulatory proteins and the basal RNA polymerase II transcription machinery. Mediator is recruited to promoters through direct interactions with transcriptional regulators and serves as a scaffold for assembly of the pre-initiation complex with RNA polymerase II and general transcription factors. Contributes to phosphorylation of transcription factors and other substrates, including RNA polymerase II and the Notch1 intracellular domain (ICN1), thereby modulating gene expression programs. Plays a role together with CDK8 in normal macrophage differentiation (By similarity).
Synonyms: CDC2L6; CDK11; KIAA1028; bA346C16.3; DEE87; EIEE87
Tractability: Small molecule: a drug acting on it is in phase 2 or 3 trials; a high-quality ligand is known; it belongs to a druggable protein family. PROTAC: ubiquitination databases record sites on it; its protein half-life has been measured; a small molecule that binds it is known.
Target class: Protein Kinase; CMGC protein kinase CDK family; CMGC protein kinase group; CMGC protein kinase CDK8 subfamily; Kinase; Enzyme
Chemical probes: BI-1347 (high quality), CCT251545 (high quality), Cortistatin-A, MSC2530818 (high quality)
Gene: Protein-coding gene on chromosome 6 (110,609,978 to 110,815,958, reverse strand). Ensembl gene ENSG00000155111.
Subcellular location: Cytoplasm; Cytoplasm, perinuclear region; Nucleus
Subcellular location (Human Protein Atlas): Cytosol; Nucleoplasm
Pathways (Reactome):
Developmental Biology: Transcriptional regulation of white adipocyte differentiation
Disease: RSV-host interactions
Metabolism: PPARA activates gene expression
Gene Ontology:
Molecular function: protein serine/threonine kinase activity; cyclin-dependent protein serine/threonine kinase activity; ATP binding; protein kinase activity; protein serine kinase activity
Biological process: regulation of transcription by RNA polymerase II; cellular response to lipopolysaccharide; positive regulation of apoptotic process; regulation of cell cycle
Cellular component: cytoplasm; cytosol; nucleoplasm; nucleus; CKM complex; perinuclear region of cytoplasm
Genetic constraint (gnomAD): Loss-of-function variants: 10 observed, 25.91 expected, observed/expected ratio (o/e) 0.39, 90% interval 0.24 to 0.65. The upper end of that interval is the gene's LOEUF score, 0.65, which puts it in group 2 of 6, group 1 being the genes least tolerant of losing a copy. Missense variants: 190 observed, 327.05 expected, observed/expected ratio (o/e) 0.58, 90% interval 0.51 to 0.65. Synonymous variants: 127 observed, 131.01 expected, observed/expected ratio (o/e) 0.97, 90% interval 0.84 to 1.12.
Homologues: Orthologues: chimpanzee CDK19 (100% identical), macaque CDK19 (99% identical), pig CDK19 (98% identical), rabbit CDK19 (98% identical), dog CDK19 (97% identical), guinea pig CDK19 (97% identical), mouse Cdk19 (96% identical), rat Cdk19 (96% identical), zebrafish cdk19 (86% identical), tropical clawed frog cdk19 (85% identical), Drosophila melanogaster Cdk8 (66% identical). Paralogues in human: CDK8 (78% identical), CDK13 (29% identical), CDK12 (28% identical), CDK11A (26% identical), CDK11B (26% identical), CDK7 (26% identical), CDK16 (26% identical), CDK1 (26% identical), CDKL5 (26% identical), CDK17 (26% identical), CDK10 (25% identical), CDK3 (25% identical), and 14 more.
Diseases named in the same sentence as CDK19 in open-access papers:
CDK19 is named in the same sentence as 72 diseases in open-access papers, as found by Europe PMC text mining. Sharing a sentence is not in itself a finding about the gene and the disease. The quoted sentences say what the papers report.
prostate carcinoma (25 papers, 2016 to 2025). A carcinoma that arises from epithelial cells of the prostate gland. "CDK19 has been strongly associated with prostate cancer due to its distinct and elevated expression in malignant and metastatic prostate tissues compared to normal tissues." (PMID 40361480, 2025). "Increased levels of CDK8 and CDK19 are associated with a higher migratory potential in prostate cancer cell lines." (PMID 40163908, 2025). "CDK19 is associated with increased aggressiveness and shorter disease-free survival in primary prostate cancer." (PMID 37835536, 2023). "Elevated mediator complex sub-type CDK19 expression associated with aggressiveness of prostate cancer; Pan-Cancer Analysis of the Mediator Complex Transcriptome determined CDK19 and CDK8 as treatment targets in late-period prostate carcinoma." (PMID 35627232, 2022). "Both deletions and amplifications were especially notable among prostate cancers, where increasing expression of CDK19 and CDK8 has been shown to be associated with carcinogenesis and acquisition of the largely incurable CRPC phenotype." (PMID 31382571, 2019). "In comparison, although information on CDK19 has been limited, the CDK19 gene has been recently implicated in prostate cancer." (PMID 29568371, 2018). "Preclinical studies with T-474 and T-418, two structurally distinct CDK8/CDK19 inhibitors, demonstrated induction of prostate cancer cell death and significant anti-tumour activity in CRPC xenografts." (PMID 40163908, 2025). "Functional studies demonstrated that CDK19 knockdown had limited effects on cell viability; it markedly reduced migration and invasion in prostate cancer cell lines, suggesting its role in metastatic progression." (PMID 40361480, 2025). "MED12 mRNA expression was positively correlated with CDK8 and CDK19 gene expression in multiple primary prostate cancer tissue datasets, as expected by their common presence in the kinase module." (PMID 39253786, 2024). "For example, lncRNA NEAT1-1 promotes bone metastasis of prostate cancer via modulating CYCLINL/CDK19 complex, reliant on m6A-modified sites." (PMID 37257820, 2023). "CDK19, as a critical regulatory enzyme, has been reported to promote tumor cell migration and proliferation in prostate cancer and ovarian cancer." (PMID 36259156, 2023). "In contrast, the role of CDK19 in carcinogenesis is rarely studied and only sporadically reported in prostate cancer, colorectal cancer, breast cancer, etc.." (PMID 34649520, 2021). "These phenotypic characteristics are similar to those of CDK19 in prostate cancer, gastric cancer, and head and neck squamous cell carcinoma." (PMID 34649520, 2021). "We found that both of CYCLINL1 and CDK19 were highly expressed in bone metastatic prostate cancer tissues." (PMID 33308223, 2020). "In contrast, CDK19 RNA expression was relatively uniform among different cancers, with a prominent elevation in prostate cancers, where CDK19 has been already identified as a marker of carcinogenesis and tumor progression." (PMID 31382571, 2019). "In contrast, at the protein level, CDK19 expression in tumor cell lines (other than prostate cancer) is generally much lower than the expression of CDK8 (our unpublished data), suggesting post-transcriptional regulation of CDK19." (PMID 31382571, 2019). "CDK19 expression was relatively uniform, except for much higher levels in prostate cancers relative to all the others." (PMID 31382571, 2019). "We then investigated the expression of CDK8 and CDK19 in several commercially available prostate cancer cell lines." (PMID 29568371, 2018). "In accordance with previous reports, CDK19 was highly expressed in some prostate cancer cells at the mRNA and protein levels." (PMID 29568371, 2018). "CDK19 inhibition induced G1/S transition in prostate cancer cells." (PMID 38360723, 2024). "Furthermore, a previous study has also focused on high expression of both CDK8 and CDK19 in prostate cancer metastases." (PMID 33868579, 2021).
prostate carcinoma (continued). "Inhibition of Mediator kinases CDK19 and CDK8 suppresses androgen-independent in vivo growth of castration-resistant prostate cancers via castration-induced transcriptional reprogramming in tumor and stromal cells." (PMID 38546787, 2024). "As RUNX2 is a widely known vital marker and driver in bone metastatic prostate cancer, this CCNL1/CDK19/NEAT1-1 complex can significantly induce the bone metastasis of prostate cancer." (PMID 37069649, 2023). "We also generated derivatives of 22Rv1 prostate cancer cells (which overexpress CDK19 relative to CDK8) with the knockout of CDK8 and CDK19, individually and in combination (dKO), and analyzed STAT1 S727 phosphorylation with and without IFNγ treatment." (PMID 37378433, 2023). "In contrast, CDK19 knockout had a stronger effect than CDK8 knockout on STAT1 S727 phosphorylation and a similar effect on gene expression in 22Rv1 prostate carcinoma cells that overexpress CDK19 relative to CDK8." (PMID 37378433, 2023). "CDK19 was the cancer-related gene most highly correlated with ETV4 expression, confirming its oncogenic function in ETV4-fusion-positive prostate cancer." (PMID 36289913, 2022). "CDK19 is a paralog of CDK8 and was identified as a therapeutic target in prostate cancer and leukemia." (PMID 33686962, 2021). "On the contrary, CDK19 and NOS2, overexpressed during prostate cancer progression, were induced in NE-like tumors and down-regulated in DHT-treated OSC." (PMID 32041153, 2020). "It is possible that CDK19, the paralog of CDK8, can compensate for the loss of CDK8 in the adult organism in non-transformed tissues, as proposed in NK43 and prostate cancer cells." (PMID 31628323, 2019). "While differentially expressed subunits in testicular (n = up to 23) and pancreatic tumors (n = 12) were found with a frequency of 100%; only low frequencies for over- (30% in CDK19, n = 121/404) and underexpression (8% in MED22, n = 23/290) were detected in prostate cancer." (PMID 27050271, 2016). "CDK19 expression is also elevated in prostate cancer and correlates with shorter disease-free survival; interestingly, upregulation of this kinase appears to be specific to prostate cancer and not other tumour types." (PMID 40163908, 2025).
breast cancer (8 papers, 2017 to 2021). A primary or metastatic malignant neoplasm involving the breast. "In the same study, we found that higher expression of CDK8, CDK19 and Cyclin C is associated with shorter relapse-free survival in human breast cancers." (PMID 28147342, 2017). "Meanwhile, it was reported that high expression of CDK19 is associated with poor prognosis of breast cancer patients with enhancement of estrogen receptor signaling." (PMID 28885545, 2017). "Among those CDKs, the expression levels of CDK10 and CDK19 were significantly higher in breast cancer than in normal breast tissues in Oncomine and the HPA datasets." (PMID 33686962, 2021). "CDK8/CDK19 inhibitors suppress the growth of estrogen receptor-positive breast cancer cells and reduce the emergence of estrogen-independent cells." (PMID 31248103, 2019). "The other cancers with a substantial frequency of CDK8/CDK19/CCNC gene amplification were breast cancers and sarcomas." (PMID 31382571, 2019). "In particular, co-amplification of CDK8 with CCNC and/or CDK19 was found in some cases of prostate and breast cancer." (PMID 31382571, 2019). "Further functional investigation on the mechanism of transcriptional regulation by CDK19 in breast cancer cells would be required to clarify the apparently opposite roles of CDK19 among different studies." (PMID 28885545, 2017). "Analysis of the transcriptome data of 968 breast cancer patients has uncovered increased levels of CDK8/CDK19 paralleled by enhanced levels of cyclin C and MED13 compared to samples from patients with benign or hyperplastic breast cancers and from normal mammary tissues." (PMID 31248103, 2019). "Chemical inhibition of CDK8/CDK19 or genetic knockdown of CDK8 impaired cell growth and progression of this breast cancer type in vitro and in vivo." (PMID 34689158, 2021). "The results revealed that the mRNA expression of CDK7, CDK8, CDK9, CDK10, CDK12, CDK19, and CDK20 was upregulated in patients with breast cancer." (PMID 33686962, 2021). "In contrast, CDK8, CDK19, and CCNC showed similar amplification frequencies in breast cancers and sarcomas." (PMID 31382571, 2019). "CDK13 and CDK19 were not expressed or lowly expressed in normal breast tissues, whereas medium expression of these two proteins was observed in breast cancer tissues." (PMID 33686962, 2021). "Furthermore, the SNP pair ranking fourth map to CDK19 and CCDC162P genes, which are both shown to be affected in breast cancer." (PMID 32957998, 2020). "Indications of the mechanisms come from human pancreatic and ovarian cell lines and a murine breast cancer model, in which the inhibition of CDK8/CDK19 counteracts EMT by upregulating E-cadherin, downregulating Snail1 and Snail2, and reducing tumor cell invasion." (PMID 31248103, 2019). "The function of CDK19 in breast cancer is not verified at present, but CDK8 acts downstream of the estrogen receptor as estrogen-induced transcription depends on CDK8 kinase activity." (PMID 31248103, 2019). "Expression of CDK8, its paralog CDK19 and their binding partner Cyclin C are negative prognostic markers in breast cancer." (PMID 28147342, 2017). "Although the inhibition of CDK8/CDK19 fails to induce apoptosis, synergistic effects in combinatorial therapies might be beneficial for breast cancer patients." (PMID 31248103, 2019). "The results showed that although the mRNA expression of CDK7, CDK8, CDK19, and CDK20 was higher in breast cancer tissues, none of these transcripts’ values reached statistical significance." (PMID 33686962, 2021).
acute myeloid leukemia (6 papers, 2015 to 2025). Acute myeloid leukemia (AML) is a group of neoplasms arising from precursor cells committed to the myeloid cell-line differentiation. "Mediator-associated kinases cyclin-dependent kinase 8 (CDK8) and CDK19 prevent the increased activation of key super-enhancer-associated genes in acute myeloid leukemia (AML) cells." (PMID 37190100, 2023). "An example supporting redundant functions for CDK8 and CDK19 was reported in acute myeloid leukemia cells treated with the CDK8/CDK19 kinase inhibitor CA." (PMID 28416637, 2017).
leukemia (5 papers, 2015 to 2023). A malignant (clonal) hematologic disorder, involving hematopoietic stem cells and characterized by the presence of primitive or atypical myeloid or lymphoid cells in the bone marrow and the blood. "CDK8 and CDK19 were found to cooperate with each other in supporting leukemia cell growth, stimulating NFκB-induced transcription and Dengue virus replication." (PMID 37378433, 2023). "As Cdk8/Cdk19 inhibition has been reported to suppress cell proliferation in leukemia, we further analyzed the cell proliferation by CFSE labeling in the presence of CCT251921." (PMID 31552016, 2019). "While CDK19 is downregulated in leukemia, lymphoma and esophageal cancer, CDK8 is overexpressed and amplified in ~50% of colon cancers suggesting a selective role of CDK8 in this type of tumors." (PMID 25914884, 2015). "In human, CCNC and CDK19 genes lie very close to each other on the 6q21 region of the human chromosome 6, a region that is frequently deleted in multiple malignancies including breast, lung, ovarian, prostate carcinomas, leukemia and osteosarcoma." (PMID 25914884, 2015). "To evaluate the phenotypic effects of CDK8 and CDK19 in other cell lines, we have generated HAP1 leukemia derivatives with the knockout of CDK8, CDK19 or both CDK8 and CDK19 (dKO)." (PMID 37378433, 2023). "Although murine leukemia cells (BCR-ABL1p185+) contain high levels of CDK6, CDK7, CDK8, CDK9, and CDK19, knockdown of CDK6, CDK7, CDK9, or CDK19 has little effect on cell survival and proliferation in an inducible system." (PMID 31628323, 2019).
liver cancer (4 papers, 2021 to 2024). An epithelial or non-epithelial malignant neoplasm that arises from the liver. "In various liver cancer cell lines exposed to high glucose conditions, CA inhibited the activity of cyclin-dependent kinase 19 (CDK19) that in turn reduced the Yes-associated protein (YAP)-O-GlcNAcylation pathway and thus decreased cancer cell proliferation and tumor growth." (PMID 36012159, 2022). "In addition, we found that YAP and OGT were positively associated with cyclin-dependent kinase 19 (CDK19) in liver cancer tissues and cell lines." (PMID 34588426, 2021). "Studies have demonstrated that corosolic acid possesses the ability to diminish the level of cyclin-dependent kinase 19 (CDK19)-mediated O-GlcNAcylation within liver cancer cells, thereby impeding the advancement of cancer." (PMID 38915462, 2024). "We found that CA treatment inhibited the global level of O-GlcNAcylation and the expression of YAP through CDK19, which eventually inhibited the transformative phenotypes of liver cancer cells." (PMID 34588426, 2021). "In Senexin B-treated liver cancer cells, HG was unable to induce an enhanced transformed phenotype, further illustrating that CDK19 is required in HG-stimulated liver tumorigenesis." (PMID 34588426, 2021). "To better investigate the biological function of CDK19 in the O-GlcNAcylation of liver cancer cells, we knocked out or overexpressed CDK19 and found a critical role for CDK19 in O-GlcNAcylation levels in liver cancer cells." (PMID 34588426, 2021). "Here we found that CDK19 and O-GlcNAcylation were positively correlated in liver cancer tissues and cell lines." (PMID 34588426, 2021). "Collectively, these results demonstrate that CDK19 promoted cellular O-GlcNAcylation of liver cancer cells in an OGT-dependent manner." (PMID 34588426, 2021). "Overall, this finding suggests that CA negatively regulates CDK19 to reduce the cellular O-GlcNAcylation level and suppress the proliferative capacity of liver cancer cells." (PMID 34588426, 2021). "Chlorogenic acid was found to reduce cell proliferation by attenuation of the CDK19/YAP/O-GlcNAcylation pathway in liver cancer, indicating that chlorogenic acid could serve as a compound for treating diabetes-associated liver cancer." (PMID 39199296, 2024). "Therefore, we confirmed that CDK19 participates in the regulation of O-GlcNAcylation in liver cancer cells, specifically through YAP and OGT." (PMID 34588426, 2021). "We subsequently investigated whether CA attenuated the increase in global O-GlcNAcylation and inhibited the suppression of liver cancer cell proliferation through CDK19." (PMID 34588426, 2021). "We found that the levels of OGT, YAP, and O-GlcNAcylation in liver cancer cells with CDK19 knockout were increased compared to those treated with CA alone, suggesting that CA downregulates global O-GlcNAcylation in liver cancer cells in a CDK19-dependent manner." (PMID 34588426, 2021). "Next, we performed IHC to detect CDK19 in paired liver cancer tissues." (PMID 34588426, 2021). "Higher levels of CDK19 expression were found in liver cancer tissues than in normal tissues." (PMID 34588426, 2021). "Through online analysis of the GEPIA database, we found that there was a significant correlation between the expression of CDK19 and OGT in liver cancer, with a correlation coefficient of 0.44." (PMID 34588426, 2021). "As a kinase, CDK19 may inhibit the phosphorylation of OGT and thus promote O-GlcNAcylation in liver cancer cells." (PMID 34588426, 2021).